CCL7 (C-C motif chemokine ligand 7)
Diseases named in the same sentence as CCL7 in open-access papers (continued):
Sharing a sentence is not in itself a finding about the gene and the disease.
tumor (continued). "This process is dependent on the secretion of the chemokine CCL7 by adipocytes, which diffuses from PPAT to the peripheral zone of the prostate, stimulating the migration of CCR3 expressing tumour cells." (PMID 26756352, 2016). "Each of these chemokines was consistently expressed in all of the MCA-induced tumours tested and expression of most, namely CCL2, CCL7, CCL8, CCL12 and CX3CL1, was detectable only in the tumours and not in spleen and lymphoid tissue." (PMID 25495686, 2015). "A fusion between a tumor antigen and chemokine CXCL10 or CCL7 has been demonstrated to increase immune responses in immunized mice, and to protect against tumor challenge." (PMID 26257735, 2015). "Tumor-associated macrophages (TAMs) are derived mostly from circulating monocytes which are attracted into tumor sites by locally produced chemotactic factors, such as CCL2, CCL5, CCL7, CCL8, and CXCL12, and macrophage colony stimulating factor (M-CSF)." (PMID 24966464, 2014). "Different C-C motif ligand-chemokines (CCL) and C-X-C motif ligand chemokines (CXCL), such as CCL2, CCL7, CXCL1 and CXCL6, are also potent stimulators of pro-malignant features, such as tumor cell proliferation, migration and invasion, as well as angiogenesis." (PMID 24887580, 2014). "CAFs produce CCL2, CCL5, CCL7, CXCL8, and CXCL14 and these chemokines promote tumor progression mainly by enhancing the motility of tumor cells." (PMID 24966464, 2014). "In turn, activated fibroblasts secrete HGF, CCL7, UPAR, VEGF, and other factors that promote stemness, growth, survival, and invasiveness of tumor cells." (PMID 24818101, 2014). "At least some of the recruited cells are known to support tumor growth, such as macrophages (by CCL-2 and CCL-7) and T-regulatory cells (by CCL-17)." (PMID 22348096, 2012). "Hypomethylated genes in the TNF network were cytokines (CCL3, CCL4, CCL7, CCL8, CCL22, IL21, IL17A, EBI3) that can either stimulate or inhibit tumor growth and progression." (PMID 22768131, 2012). "It was recently reported that FMRP does not impact tumor cell growth but facilitates immune evasion by controlling CCL7, IL-33, and PROS1." (PMID 41513619, 2026). "Among them, the chemokine family, including CC (e.g., CCL1, CCL3, CCL5, CCL7, and CCL15), CXC (e.g., CXCL1, CXCL3, CXCL5, and CXCL10), XC (e.g., XCL1 and XCL2), and CX3C (e.g., CX3CL1), plays a pivotal role in tumor development, metastasis, and chemotherapy resistance 30-33." (PMID 40740234, 2025). "Multiplex bead-based ELISA (Luminex) analysis of cell culture supernatant from 4T1 Vector, 4T1 MerTK C8, and 4T1 MerTK C11 tumor cells revealed significantly increased release of the pro-inflammatory cytokines IL-1 alpha and IL-31, and chemokines MCP-1 (CCL2) and MCP-3 (CCL7)." (PMID 40391157, 2025). "In addition, Western Blot analysis showed that CCL7 increased the expressions of p‐PI3K and p‐AKT in tumor tissues compared with the control group." (PMID 40062588, 2025). "In addition, monocytes (Hp+ and Ccl7+ monocytes) and conventional type 2 DCs (cDC2s) contributed to the total Il23a expression in the TME, with only negligible amounts in tumor-infiltrating T cells (TILs)." (PMID 38356059, 2024). "Notably, treatment-induced tumor volume reduction correlated with decreased levels of CCL-2, CCL-7, and CCL-12 and increased levels of CXCL-10, CCL-24, CXCL-12, and IL-3." (PMID 38575562, 2024). "CCL7 (C–C Motif Chemokine Ligand 7, aka Monocyte Chemoattractant Protein 3, MCP3) is a member of the C–C subfamily of chemokines, which plays a role in macrophage recruitment during inflammation and in tumor metastasis." (PMID 38736470, 2024). "Notably, our computational analysis of this high-dimensional data suggests that the key changes correlating with inhibition of tumor growth include the downregulation of CCL-2, CCL-7, CCL-12, and the upregulation of CXCL-10, CCL-24, CXCL-12 and IL-3." (PMID 38575562, 2024).
tumor (continued). "Thus, observed decreases in CCL2, CCL7 and CCL12 suggest a reduction in factors that promote pro-tumor, M2-like macrophage differentiation and infiltration." (PMID 38575562, 2024). "In conclusion, the anti-tumor effects induced by anti-PD-1 antibody treatment were found to be attenuated in STZ-induced diabetic mice, which was accompanied by decreased infiltration of CD11c+ cells and CD8+ T cells and decreased expression of CCL7 and CXCL9." (PMID 37046033, 2023). "Four of these cytokines (MCP-3/CCL7, PDGF-AB/BB, IL-13, and IL-3) showed significance in all analyses performed in our study (CMs vs. controls, GEP Class 2 vs. Class 1 CMs, and correlations with tumor dimensions)." (PMID 37509362, 2023). "The chemokine CCL7 secreted by PPAT was reported to mediate interactions between PPAT and PCa cells through the CCR3/CCL7 axis, promoting the extraprostatic extension of tumour." (PMID 37042512, 2023). "These genes include markers of alternative macrophage polarization (Arg1, Cd163), monocyte chemoattractant Ccl6, and ligands for CCR2 (Ccl2, Ccl7, Ccl12) and CCR5/1 (Ccl3, CCl4, Ccl9) suggesting that F4/80+ cells in these tumours represent an increase in TAM2‐like myeloid cells." (PMID 35924447, 2023). "Cytokine analysis of tumor spheroid culture media also showed that treatment with anti-CSF-1R Ab or CSF1R/CCR2/TGF-β Ab resulted in reduced release of monocyte chemoattractant proteins CCL2 and CCL7 by 231 TFM spheroids." (PMID 38076998, 2023). "KLF15 inhibits tumor behaviors, and downregulates CCL2 and CCL7, we were eager to find out whether the downregulation of CCL2 and CCL7 had effects on KLF15-mediated proliferation, migration and invasion suppression." (PMID 36347994, 2022). "CAFs secrete various soluble ligands such as CXCL12, CCL7, and TGF-β, which may interact with tumor cells and promote tumor progression." (PMID 35953863, 2022). "In the tumor microenvironment, CAFs can promote HCC metastasis by secreting CCL7 to mediate EMT." (PMID 35281057, 2022). "Using in vitro co-cultures of breast and prostate cancer cells with lymphatic endothelial cells (LEC), Oliveira-Ferrer demonstrated tumor-dependent induction of C3, CFB and C1q secretion as well as that chemokine upregulation (CCL7, CXCL6, CXCL1) by the LECs promotes tumor metastasis." (PMID 35860237, 2022). "Notably, CCL7, TAPBP, and ICAM1 were leading edge genes for all three pathways, and both CCL7 and ICAM1 were also trending up in the 14-day primary tumor proteomic analysis." (PMID 35727842, 2022). "Furthermore, CCL7, also known as monocyte chemotactic protein 3 (MCP-3), is expressed by various types of cells under physiological conditions and by tumor cells, leukocytes, endothelial cells, and fibroblasts under pathological conditions." (PMID 35406450, 2022). "Taken together, we opine that LINC01094 binds to SPI1 and promotes its nuclear translocation, which therefore binds to CCL7 promoter and activates its transcription, leading to increased chemotaxis and M2 skewing of macrophages in LUAD and aggravated tumor progression." (PMID 36118415, 2022). "The results showed that the level of CCL7 in serum was significantly higher in CRC patients with tumor metastasis or short-term recurrence than those without metastasis or recurrence." (PMID 33986252, 2021). "Interestingly, CCL7, CCL19, CXCL7, NRG3, SLPI, OPN, and HGF in macrophages are upregulated in response to increased tumor CCL5 expression." (PMID 34298673, 2021). "Tumor CCL2 and CCL7 increased along with advancing T and CCL3, and CCL4 along with the N stage." (PMID 34885960, 2021). "Our results suggested that administration of CCL7 through the intranasal pathway promoted the recruitment of cDC1 into the tumor-burdened lungs and subsequent expansion of CD8+ and CD4+ T cells in the bronchial LNs and tumor-burdened lungs." (PMID 33257678, 2020).
tumor (continued). "Interestingly, the tumor burden and growth were comparable in DT-treated KP and KP7 mice, indicating essential roles of CCL7-mediated recruitment of CD11c+ DCs in suppression of tumorigenesis in the KP mouse model." (PMID 33257678, 2020). "Our results suggest that metastatic tumor cells induce CCL7 expression in LECs that, in turn, might attract further CCR3-positive tumor cells promoting tumor cell dissemination through lymphatics." (PMID 31963450, 2020). "However, the protein levels of CCL7 as determined by IHC and IOD analysis were comparable between early and late-stage NSCLC tumor tissues." (PMID 33257678, 2020). "In addition, we observed that the intensities of CCL7 and CD11c+ cells were positively correlated in human NSCLC tumor biopsies and CD11chiCCL7hi patients showed significantly increased OS compared to CD11cloCCL7lo patients." (PMID 33257678, 2020). "This implies that the mechanism in which CAFs protect tumor cells from FSS involves forming stable cell aggregates that can persist even when subjected to FSS over 1,000 dyn/cm2 along with the secretion of soluble factors such as CCL2, CCL7 and CXCL5." (PMID 32256977, 2020). "Regardless of the tumor type or tumor site, Ly6c1high CAFs (iCAFs) showed enrichment for Il33, Il6, Ccl7, Cxcl1 and Cxcl12 whereas α-SMAhigh CAFs (myCAFs) expressed high levels of Tgfb1, Tgfb2 and Ctgf." (PMID 32455670, 2020). "Acid-induced NF-κB activation downstream promotes the secretion of several cytokines, chemokines, and growth factors (IL1a, IL1b, IL6, IL8, IL23a, CCL5, CCL7, CXCL2, GM-CSF, and G-CSF) that can elicit local cancer aggressiveness, tumor immune escape, and tumor-induced nociception and hyperalgesia." (PMID 30825056, 2019). "Other chemokines, for example, CCL7, CCL20, CXCL1, and CXCL17, demonstrate similar expression patterns and may also be important contributors to MØ tumor infiltration, MØ differentiation, and a more aggressive phenotype." (PMID 30451357, 2019). "Conversely, the lower Ccl5 to Ccl7 and Ccl5 to Ccl2 expression ratios in F5-T1 support a TME containing less T-lymphocyte chemoattractants and with a greater inflammatory reaction, also attested by the maximal fibrinogen content that characterized this tumor." (PMID 29662647, 2018). "CCL7 activates the TGF-β pathway by enhancing Smad2 phosphorylation, and blocking the TGF-β pathway markedly inhibits the effects of CCL7 on tumor migration and invasion, highlighting the role of CCL7 in regulating tumor progression by influencing the tumor microenvironment via the TGF-β pathway." (PMID 29915688, 2018). "As speculated, CCL7 and CCR3 mRNA expression levels in liver metastatic tissue were significantly higher than those in primary tumor tissue." (PMID 27167205, 2016). "Mechanically, TAMs are generally recruited from blood monocytes by diverse chemokines such as CCL2 (MCP-1), CCL5, CCL7, CXCL8 and CXCL12, migrate to diverse areas of the tumor microenvironment and differentiate according to surrounding cellular or environmental stimuli." (PMID 25685069, 2015). "Similarly, CXCL5, CXCL13, CCL1, CCL7 and CCL26 in WF collected from patients with T1–2 tumor tend to be higher than those with Tis, and the profiles of CXCL13, CCL27, MMP-1 and MMP-7 in WF from N1–3 patients tend to be higher than those with N0." (PMID 26313265, 2015). "These analyses revealed that the tumours are characterized by expression of inflammatory chemokines (CCL2, CCL5, CCL7, CCL8, CCL12, CXCL9, CXCL10 and CX3CL1), reflected by an enrichment of activated Foxp3− and Foxp3+ T cells expressing T helper type 1-associated chemokine receptors." (PMID 25495686, 2015). "The negative correlation between let-7d expression and CCL7 in T3 stage RCC tissues additionally highlights the role of CCL7 in tumor invasion and metastasis." (PMID 25193015, 2014). "This study demonstrated that let-7d may suppress RCC growth, metastasis and tumor macrophage infiltration at least partially through targeting COL3A1 and CCL7." (PMID 25193015, 2014).
tumor (continued). "Several CC chemokine members, including CCL2 (MCP-1), CCL3 (MIP-1α), CCL5 (RANTES), CCL7 (MCP-3), CCL8 (MCP-2), CCL17 (TARC) CCL 20 (MIP-3α), CCL22 (MDC) and CCL23 (MPIF-1), are produced mainly by tumor infiltrating lymphocytes (TIL) and monocytes, and some of them also by cancer cells." (PMID 24213462, 2012). "Tumor-associated macrophages (TAM) derive mostly from circulating monocytes which are attracted into tumor sites, by locally produced chemotactic factors, such as CCL2, CCL5, CCL7, CCL8, CXCL12, vascular endothelial growth factor (VEGF), and macrophage colony stimulating factor (M-CSF)." (PMID 24212934, 2011). "Likewise, interferon response genes (including TLR3, MX1, RSAD2, IFI44, IFI27, IFIT1, and IFIT3), and chemokine genes (including CCL7, CXCL10, CXCR1, and CCL25) were significantly increased in PM-treated MM tumor tissues, whereas panobinostat showed minimal effects at equivalent doses." (PMID 40562746, 2025). "By analyzing the effect of MAP2K3 expression levels on chemokines in the tumor immune microenvironment, the results showed elevated expression of several chemokines in the MAP2K3 high expression group; such as CXCL10, CCR5, CCR10, CCL5, CCL7, CCR2, and CCL22 (upper part)." (PMID 38938778, 2024). "The expression levels of ccl-2 (MCP-1), ccl-20 (MIP-3), ccl-7 (MCP-3), CXCL-4 (PF-4), CXCL 1 (Gro -), and CXCL-12 (SDF-1) are also significantly increased in replicative senescent cells, allowing the disruption of the blood-tumor barrier integrity and greater spread of tumor cells." (PMID 37450933, 2024). "For example, SDG CCL7 showed an obvious difference between cluster 0 and other clusters based on SPE, while its raw spatial expression is completely messy and shows no obvious difference, indicating the ability of stMGATF to reveal biological variation among tumor areas." (PMID 37736108, 2023). "Bone marrow-derived cells from tumor-bearing animals 3-week post-implantation displayed statistically significant migration, achieving maximum migration of 500% and 334% at a plating concentration of 10ng/mL and 30ng/mL for CCL2 and CCL7 respectively (p<0.0001)." (PMID 36685592, 2022). "Tumor-derived factors such as colony-stimulating factor 1 (CSF1; also known as M-CSF), granulocyte-macrophage colony-stimulating factor (GM-CSF), CC-chemokine ligand 2 (CCL2), CCL7 (or MCP-3), GDNF, IL-33, CXCL12 (SDF-1) and EGF are responsible for myeloid cell recruitment and promote tumor growth." (PMID 36140392, 2022). "In addition to cancer cells, non-malignant cells in the tumor microenvironment, including fibroblasts, adipocytes, and macrophages, were found to produce CCL7." (PMID 34206004, 2021). "Interestingly, we found that the numbers and percentages of CD11c−CD11b−Ly6c+ monocytes were comparable between the tumor-burdened lungs of KP mice and KP7 mice, indicating that CCL7 is dispensable for monocytes infiltration into the lungs of KP mice after tumor induction." (PMID 33257678, 2020). "This autocrine secretion could lead to the absence of a CCL7 gradient between tumour cells and Ad-CM, therefore, hindering directed migration." (PMID 26756352, 2016). "In summary, our results indicate that the tumor suppression role of let-7d in RCC may be partially ascribed to its ability to decrease collagen expression and macrophage recruitment through targeting COL3A1 and CCL7 mRNAs." (PMID 25193015, 2014). "In addition, the KP and KP7 tumors displayed similar cell proliferation rate as indicated by Ki67 staining, suggesting that CCL7 might not directly modulate tumor cell proliferation." (PMID 33257678, 2020). "Flow cytometry analysis showed that OPN treatment increased the percentage of cells in S phase, while CCL7 and TSP1 did not, suggesting that OPN stimulates tumor cell proliferation." (PMID 26046767, 2015). "While no statistical differences in IL-1β, CCL-7, CCL-8, CCL-24 and CXCL-5 gene expression were confirmed among four tumor groups." (PMID 24260500, 2013).
tumor (continued). "In contrast, tumor cells with low or absent FMRP expression promote the secretion of CCL5, CXCL9, and CXCL10 from macrophages to create an immune activation microenvironment in cooperation with CCL7." (PMID 36968189, 2023). "Also, monocyte mobilization from bone marrow was previously reported to be managed by CCL7 (MCP-3) and recently found to be specifically upregulated in immature monocytes and neutrophils derived from NSCLC patient tumor parenchyma compared to adjacent non-neoplastic lung tissue." (PMID 35493461, 2022).